CRP (C-reactive protein)
Diseases named in the same sentence as CRP in open-access papers (continued):
Sharing a sentence is not in itself a finding about the gene and the disease.
Inguinal hernia (6 papers, 2013 to 2025). Protrusion of the contents of the abdominal cavity through the inguinal canal. "The primary aim of this study is to investigate whether rTAPP repair of both simple and complex inguinal hernias is associated with a lower surgical stress response, as indicated by CRP levels." (PMID 39118135, 2024). "In patients with inguinal hernia, serum IL-6, CRP, and MMP-9 increase first and then decrease after surgery, reaching the peak value around 24 or 48 h after surgery." (PMID 40292257, 2025). "This indicates that preoperative serum IL-6 and CRP levels affect the prognosis of patients with inguinal hernia." (PMID 40292257, 2025). "Given that inguinal hernia repair is less invasive than colonic resection, a smaller difference in CRP levels was anticipated." (PMID 39118135, 2024). "This assumption was grounded on a study from 2019, which reported an average CRP value of 16.5 mg/L 24 h post-TAPP surgery for inguinal hernia repair." (PMID 39118135, 2024). "The C-reactive protein response to inguinal hernia repair has been described on numerous occasions, but with the goal of comparing operative technique rather than studying host characteristics which determine the inflammatory response." (PMID 23391158, 2013). "Serum IL-6, CRP, and MMP-9 levels in patients with inguinal hernia can affect the efficacy of modified preperitoneal Kugel repair and the prognosis of patients." (PMID 40292257, 2025). "Therefore, serum IL-6, CRP, and MMP-9 in patients with inguinal hernia before surgery will affect the surgical efficacy and prognosis of patients." (PMID 40292257, 2025). "No increase in CRP was observed in the patients who received spinal anesthesia, which suggests that spinal anesthesia may be a better option for inguinal hernia surgery, particularly in patients with a BMI greater than normal (>25)." (PMID 40719205, 2025).
intracranial aneurysm (6 papers, 2019 to 2025). "We aimed to explore the genetic overlap and associations between inflammation (IL6 signaling and CRP) and intracranial aneurysm (IA) risk." (PMID 34168680, 2021).
kidney cancer (6 papers, 2020 to 2026). Primary or metastatic malignant neoplasm involving the kidney. "In this study, conditional on each other and covariates, neutrophil and platelet counts, and PDW, as well as BMI and CRP, were associated positively, while lymphocyte count and HI were associated inversely with kidney cancer risk." (PMID 40790491, 2025). "CRP has also been positively associated with kidney cancer risk in prospective studies." (PMID 40790491, 2025). "In individuals with high CRP levels (≥ 3 mg/L), LE8 was linked to lower risks of overall, lung, breast, and kidney cancers." (PMID 41554683, 2026). "Our study reveals that LE8 significantly protects against lung and kidney cancer risks in individuals with elevated inflammation levels (CRP > 3 mg/L), highlighting a key interaction between LE8 and inflammation markers." (PMID 41554683, 2026). "Corresponding to the cancer-related inflammation, inflammatory cytokines are higher at kidney cancer diagnosis, although CRP itself is unlikely to have a causal role, as there was little evidence for association of genetically-predicted CRP with kidney cancer risk." (PMID 40790491, 2025).
leishmaniasis (6 papers, 2014 to 2025). Infectious disease that is transmitted through the bite of hematophagous female phlebotomine sand flies. "In leishmaniasis, there are increased levels of proinflammatory mediators including TNF-α, CRP and adenosine deaminase." (PMID 39539349, 2024). "Finally, APP, such as C-reactive protein and haptoglobin, which could support the monitoring of clinical cases of leishmaniasis, were not evaluated." (PMID 39897361, 2024).
lipodystrophy (6 papers, 2014 to 2022). A congenital or acquired disorder characterized by abnormal loss or redistribution of the adipose tissue in the body. "As expected, CRP concentrations were significantly elevated in lipodystrophy patients compared to control (3.3 ± 1.0 μg/mL, n = 9 vs. 1.4 ± 0.3 μg/mL, n = 31, p = 0.0074)." (PMID 35684160, 2022). "Age had the strongest positive association with lipodystrophy and also positively correlated with several inflammatory markers, including LBP, CRP, IL-6, ICAM-1, and serum amyloid A (SAA)." (PMID 34006628, 2021). "Plasma annexin A1 levels were decreased in patients with lipodystrophy compared to BMI matched controls (0.2 ± 0.1 ng/mL, n = 9 vs. 0.97 ± 0.1 ng/mL, n = 30, p = 0.008), whereas CRP levels were significantly elevated (3.3 ± 1.0 μg/mL, n = 9 vs. 1.4 ± 0.3 μg/mL, n = 31, p = 0.0074)." (PMID 35684160, 2022).
maturity-onset diabetes of the young (6 papers, 2018 to 2025). "This is consistent with reports showing that the loss-of-function mutations in the HNF1α-encoding gene associated with maturity-onset diabetes of the young (MODY) lead to a significant reduction in circulating CRP concentrations." (PMID 29330688, 2018).
measles (6 papers, 2014 to 2025). A highly contagious viral infection caused by the measles virus. "This study aims to evaluate the association between serum CRP changes and the severity of respiratory complications in the group of inpatients treated for measles." (PMID 39064460, 2024). "IL-6 eclipsed CRP and procalcitonin as a severity biomarker, consistent with the cytokine’s central role in measles-induced immune dysregulation and secondary viral pneumonitis." (PMID 40872832, 2025). "C-reactive protein (CRP) levels in the serum of patients with measles increase concurrently with the onset of the rash." (PMID 39064460, 2024). "The c-reactive protein level was higher in the adult group than the pediatric group (p < 0.05), suggesting that adults with measles have a more severe inflammatory response." (PMID 37161385, 2023). "In a study of 249 children, Italian researchers showed that the risk factors for severe outcomes in measles can be predicted by monitoring the CRP value without depending on the children’s age or premorbid condition." (PMID 39064460, 2024). "Only slight differences in measles duration, changes in RBC count, and CRP levels were found between the males and females with AMP." (PMID 36422189, 2022). "What is interesting to mention is that the chest X-ray changes in patients with measles do not correlate with the magnitude of CRP changes." (PMID 39064460, 2024). "The generally higher values of CRP in females could explain the relatively higher values of this protein during a reaction to morbilli infection rather than to AMP per se." (PMID 36422189, 2022).
melancholic depression (6 papers, 2017 to 2025). "Indeed, elevated CRP was previously found among individuals with atypical depression compared to those with melancholic depression." (PMID 35361785, 2022).
murine typhus (6 papers, 2012 to 2025). "Consistent with other reports, however, murine typhus was associated with elevated liver enzymes, procalcitonin, and C-reactive protein." (PMID 30882318, 2019). "Laboratory parameters outside the normal range that differed between the two forms of typhus were plasma albumin, C-reactive protein (CRP) and lactate dehydrogenase." (PMID 26317419, 2015). "Laboratory parameters that differed between the two typhus groups were plasma sodium, creatinine, albumin, C-reactive protein (CRP) and lactate dehydrogenase, although sodium and creatinine values remained within the normal range for both groups." (PMID 22192733, 2012).
Mycoplasma infection (6 papers, 2019 to 2026). "Taken together with our results, this implies that CRP might not only work as a biomarker for mycoplasma infection but also play a role in mediating the pathogenic mechanisms of mycoplasma." (PMID 37662942, 2023). "This shows that CRP levels can be a useful marker in determining the degree of remaining inflammation in mycoplasma infections, similar to other bacterial infections." (PMID 36140012, 2022). "Previous studies have shown elevated levels of CRP in patients with mycoplasma infection." (PMID 37662942, 2023). "In the present study, we observed that C. psittaci and Legionella infections could cause a more pronounced inflammatory response, including increased WBC, neutrophils, CRP and PCT, especially in patients with L. p, both compared with Mycoplasma infection." (PMID 36929690, 2023). "Besides, a growing body of evidence have shown that SLC8A1, male, infants < 6 months old, low serum albumin, high ESR, CRP, mycoplasma infection, IVIG started after the 10th day of illness and IVIG non-responders may increase the risk of CAA." (PMID 31366406, 2019).
myelofibrosis (6 papers, 2015 to 2025). A partial or complete replacement of the bone marrow stroma by fibrous tissue. "Both higher basophil and monocyte counts have been associated with unfavorable survival in myelofibrosis patients, and the same was reported for higher ferritin, CRP and LDH, RDW, and lower platelet count." (PMID 40217782, 2025). "In myelofibrosis, the C-reactive protein (CRP)/albumin ratio (CAR) and the Glasgow Prognostic Score (GPS) add prognostic information independently of the Dynamic International Prognostic Scoring System (DIPSS)." (PMID 36900271, 2023). "Regarding hematologic diseases, enhanced CRP has been found to have an impact on the clinical outcome in MPN including primary and secondary myelofibrosis, essential thrombocythemia, and polycythemia vera." (PMID 36441359, 2023).
nasopharyngitis (6 papers, 2017 to 2025). An inflammatory process that affects the nasopharynx. "The most common TEAEs (MedDRA-preferred terms) were increasing C-reactive protein, nasopharyngitis, and headache, which affected 11%, 9%, and 6% of all participants, respectively." (PMID 40520205, 2025). "For two of the patients, the increased CRP levels were considered by the investigator to be clinically significant and were reported as AEs of mild intensity, one as nasopharyngitis, and the other as CRP increase." (PMID 34330322, 2021).
neuroendocrine tumors (6 papers, 2017 to 2025). "On the other hand, preoperative CRP levels were significantly higher in patients with SCC than in patients with neuroendocrine tumors." (PMID 41509932, 2025). "In summary, higher CRP associated with carcinoma and neuroendocrine tumors, while LDH increased primarily in neuroendocrine tumors suggesting that biomarker analysis should be performed in a histology specific manner." (PMID 34257595, 2021). "Increased CRP levels (>1 mg/dl) were significantly more often measured in thymic carcinoma and neuroendocrine tumors when compared to thymoma." (PMID 34257595, 2021). "Our study clearly shows that elevated CRP is way more frequent in thymic carcinoma and neuroendocrine tumors." (PMID 34257595, 2021). "Thymic carcinoma and neuroendocrine tumor patients had more often high CRP (>1 mg/dl) than thymoma patients (30% and 44% vs 11%, p = 0.0005)." (PMID 34257595, 2021).
osteitis (6 papers, 2014 to 2025). "Measurement values of albumin, condition of “hernia of abdominal wall,” and “neoplasm of breast” were negatively associated with prolonged hospital stay, while measurement values of total bilirubin, C reactive protein, and condition of osteitis were positively associated." (PMID 37955965, 2023). "Baseline DAS28(CRP) also correlated with baseline RAMRIS-osteitis in the MCPs (0.33 (0.13–0.51)), with baseline RAMRIS-erosion in the MCPs (0.43 (0.24–0.59)), and with baseline CARLOS (0.27 (0.04; 0.48))." (PMID 29236711, 2017). "Treatment effect sizes of infliximab therapy were similar for DAS28(CRP) (1.08; 90% CI (0.63–1.53)) and MRI inflammation endpoints: wrist Ktrans (1.00 (0.55–1.45)), RAMRIS synovitis (0.85 (0.38–1.28)) and RAMRIS osteitis (0.99 (0.52–1.43))." (PMID 29236711, 2017). "DCE-MRI Ktrans and RAMRIS synovitis and osteitis showed stable disease activity with placebo treatment, and each measure had a treatment effect size with infliximab that was quantitatively similar to the DAS28(CRP) benchmark." (PMID 29236711, 2017).
ovarian tumor (6 papers, 2019 to 2023). "Our results indicate that plasma CRP levels help monitor the progression of ovarian tumor and combination of novel protein biomarkers have a good distinguishment between cancer and non-cancer patients." (PMID 33613752, 2021). "So we analyzed the changes of Cyr61, CRP and the percentage neutrophils in the peripheral blood of ovarian tumor." (PMID 31766991, 2019).
pancolitis (6 papers, 2017 to 2025). Ulcerative colitis that involves the entire colon. "When selecting the appropriate cut-off values to determine disease activity, especially the pancolitis group, hs-CRP and CAR showed higher classification and diagnostic values compared to CBC parameters." (PMID 36572872, 2022). "Furthermore, among patients with active UC, the severe subgroup demonstrated the highest proportion of pancolitis, along with the highest median of IMES, mMayo score, PLT count, CRP, and ESR levels (all p < 0.05)." (PMID 41586218, 2025). "There was a statistically significant difference between endocan levels and CRP levels between the left-distal group and pancolitis (diffuse colitis) patients (p < 0.001), but there was no statistical difference between age and MES." (PMID 37041496, 2023). "There was a statistically significant difference between endocan levels and CRP levels between the left-distal group and pancolitis (diffuse colitis) patients, but there was no statistical difference between age and MES." (PMID 37041496, 2023). "Compared with the remission group, the active group had a higher proportion of patients with pancolitis, as well as significantly higher median values for the improved Mayo endoscopic score (IMES), mMayo score, WBC count, PLT count, and CRP level (all p < 0.05)." (PMID 41586218, 2025).
peritonsillar abscess (6 papers, 2017 to 2025). An abscess that develops in the space surrounding one or both palatine tonsils. "A condensed response from o3: The numbers primarily point to acute bacterial tonsillitis (most likely streptococcal), but an early peritonsillar abscess must also be ruled if the CRP is high and the throat pain is severe." (PMID 40933813, 2025). "A study concluded that elevated CRP at the 1st and 3rd day of hospitalization (mean approx. 62 mg/L and 20 mg/L, respectively) can be an accurate parameter for the prognosis of peritonsillar abscess." (PMID 37873776, 2023). "For CRP, the highest mean values were observed in patients with peritonsillar phlegmon (109.31 mg/dL ± 90.95), followed by those with laterocervical/submandibular abscess (100.45 mg/dL ± 96.12) and peritonsillar abscess (91.21 mg/dL ± 81.88)." (PMID 40727523, 2025). "Preliminary analysis of the symptoms by using o3 (condensed, see attachment 1): The data mainly point to acute bacterial tonsillitis (most likely streptococcal), but an early peritonsillar abscess must also be excluded because if the CRP is high and severe throat pain is lasting." (PMID 40933813, 2025). "Distribution table and study cohort in total: (PTA = peritonsillar abscess, SD = standard deviation, CRP = C-reactive protein, NA-group = needle aspiration group, ID-group = incision and drainage group)." (PMID 38093972, 2023). "Chi-square analysis revealed no significant relations between CRP (χ2 = 124.05, p = 0.431), leukocyte levels (χ2 = 135.8, p = 0.301), and patients with peritonsillar abscess." (PMID 29180834, 2017).
pressure ulcers (6 papers, 2014 to 2026). "A correlation was demonstrated between CRP values (chi-square = 5.795, df = 1, p = 0.016) and creatinine levels (chi-square = 7.512, degrees of freedom = 2, p = 0.023, r = 0.25) and the occurrence of pressure ulcers in the heels of critically ill patients." (PMID 41827385, 2026). "Key predictors of pressure ulcer severity included prolonged ICU stay (p < 0.001), low albumin (Stage I: 3.4 ± 0.5 g/dL vs. Stage IV: 2.4 ± 0.8 g/dL; p < 0.001) and high CRP (Stage I: 28 mg/L vs. Stage IV: 142 mg/L; p < 0.001)." (PMID 40428232, 2025). "Patients who presented with pressure ulcers demonstrated a significant correlation between levels/counts of C-reactive Protein (CRP), Hematocrit (Hct), lymphocytes, Red Blood Cells (RBCs), White Blood Cells (WBCs), and serum proteins and the grade of the pressure ulcers." (PMID 30761068, 2019).
reactive arthritis (6 papers, 2020 to 2025). Reactive arthritis (ReA) is an autoimmune disorder belonging to the group of seronegative spondyloarthropathies and is characterized by the classic triad of arthritis, urethritis and conjunctivitis. "This patient suffered from reactive arthritis, high CRP, and exceptionally high IL-6 levels around 400 ng/mL." (PMID 40687784, 2025). "In summary, children experiencing active JIA in our study displayed a significant elevation of SII compared to those with Reactive Arthritis; furthermore, this CBC-derived index was positively correlated with both traditional inflammatory biomarkers, CRP and ESR." (PMID 38255172, 2023). "None of the trials for reactive arthritis yielded favorable results in terms of change of CRP and swollen joint count, and only one study dates back less than 15 years." (PMID 33129321, 2020).
Respiratory distress (6 papers, 2022 to 2026). Respiratory distress is objectively observable as the physical or emotional consequences from the experience of dyspnea. "The PB group showed higher rates of respiratory distress, longer hospital stays, longer fever durations, and elevated levels of neutrophil percentage, CRP, PCT, IL-6, LDH, SF, D-dimer, and ALT." (PMID 42220983, 2026). "For influenza B infections, CRP and leukocyte levels also correlated with respiratory distress, but, interestingly, for influenza A only one significant association was found, between LDH and hospitalization duration." (PMID 40430211, 2025). "For example, SOFA (the severity of respiratory distress) is directly affected by creatinine and CRP, and it is indirectly influenced by many other variables, such as gender and HYP which showed a direct effect on creatinine and CAD and NPL which showed a direct effect on CRP." (PMID 37015962, 2023).
rhinitis (6 papers, 2011 to 2025). An inflammation of the mucous membrane lining the nose, usually associated with nasal discharge. "An AR immunotherapy study showed that sublingual immunotherapy was found to simultaneously reduce interictal CRP levels and improve rhinitis symptoms." (PMID 40898461, 2025). "The association remained statistically significant, with the same odds ratio (0.95) and confidence interval (95% CI: 0.91–0.99, p = 0.035), highlighting CRP as a key predictor of rhinitis in our model." (PMID 39846516, 2024). "The two groups of patients, those prescribed antibiotics and those treated symptomatically, differed significantly in age, demand for antibiotics, days of cough, rhinitis, lung auscultation, haemoglobin level, white blood cell count, CRP level and the GP’s license to self-dispense antibiotics." (PMID 25655784, 2015). "A total of 216 adult subjects with rhinitis from the European Community Respiratory Health Survey II were investigated with multiplex component allergen analysis (103 allergen components), total IgE, C-reactive protein, eosinophilic cationic protein, fractional exhaled nitric oxide and spirometry." (PMID 32110380, 2020). "The two groups (with and without antibiotics) differed significantly with regard to age of patient, demand for antibiotics, days of cough, rhinitis, lung auscultation, haemoglobin level, WBC count, CRP measurement, and GPs’ self-dispensation of antibiotics." (PMID 25655784, 2015).
rhinosinusitis (6 papers, 2019 to 2026). "This study found that elevated CRP level was significantly associated with H. influenzae rhinosinusitis." (PMID 30685351, 2020). "The higher CRP levels in PR3-AAV may reflect ongoing rhinosinusitis, which is a common cause of low-grade inflammation in these patients." (PMID 36890852, 2023).